BDNF (brain derived neurotrophic factor)
Diseases named in the same sentence as BDNF in open-access papers (continued):
Sharing a sentence is not in itself a finding about the gene and the disease.
cognitive decline (continued). "Additionally, physical activity promotes the release of neurotrophic factors, such as brain-derived neurotrophic factor (BDNF), which supports neurogenesis and synaptic plasticity, thus offering protection against cognitive decline." (PMID 40137151, 2025). "However, overexpression of BDNF in the VGLUT1 mice’s CA1 region can significantly reduce synaptic plasticity impairment, restore neuronal excitability, and alleviate postoperative cognitive decline in mice." (PMID 38783169, 2024). "Upregulation of these IEGs, along with increased BDNF protein levels following STAT3 inhibition, suggests mechanisms by which cognitive decline could be mitigated under oxidative stress and neurodegenerative conditions." (PMID 39648181, 2024). "Importantly, the hippocampal levels of cAMP, p-PKA, p-CREB, and BDNF levels were significantly increased in RJ-treated mice, indicating the important effects of RJ on the cAMP/PKA/CREB/BDNF pathway in ameliorating cognitive decline." (PMID 38892209, 2024). "Despite increased BDNF levels from exercise, some studies suggest that elevated BDNF does not always prevent cognitive decline in certain conditions." (PMID 39935805, 2024). "Thus, glimepiride is suggested as effective in increasing BDNF and benefits T2DM in improving cognitive decline." (PMID 38001940, 2023). "This way of BDNF level determination was chosen because BDNF content in serum during aging correlates with the cognitive decline, and this effect was not previously observed in reference to plasma or platelets." (PMID 36911821, 2023). "Moreover, the results also demonstrate that samples from Group 2 exhibit a similar concentration of BDNF as the samples from Group 3, corresponding to cognitive decline alone, suggesting that insomnia may be affecting BDNF synthesis and further processing in a similar way as cognitive decline does." (PMID 37108547, 2023). "In disagreement with our previous data, the results of the present study revealed a significant negative correlation between cognitive functions and BDNF plasma concentration, suggesting higher BDNF levels in subjects with more pronounced cognitive decline." (PMID 36979505, 2023). "The importance of BDNF is further substantiated by the beneficial effects of physical exercise, which increases BDNF and TrkB expression, reduces APP processing and amyloid aggregation, and protects against cognitive decline in animal models and AD patients." (PMID 36397124, 2022). "For this purpose, we analysed data from Track-HD, a multi-centre longitudinal study in Huntington’s disease gene carriers and focused on the role of intellectual enrichment (estimated at baseline) and the genes FAN1, MSH3, BDNF, COMT and MAPT in predicting cognitive decline and brain atrophy." (PMID 36519153, 2022). "This lack of change across all methods of induced ketosis, requires further research on the level of ketosis needed to achieve an increase in BDNF levels for populations with and without cognitive decline." (PMID 36138878, 2022). "Furthermore, oral administration of Lactobacillus bacteria prevents cognitive decline in both humans and rats and improves memory retention in aged SAMP8 mice, in addition to increasing BDNF levels in the rodent brain." (PMID 35684013, 2022). "Decreased serum BDNF levels are specifically associated with fast cognitive decline in AD patients (that is, a lower MMSE score > 4 per year), rather than slow cognitive decline." (PMID 35090576, 2022). "Housing in the PI cage long-term resulted in cognitive decline and a depressive-like state with reduced hippocampal neuronal cell proliferation, hippocampal blood density, plasma VEGF level, hippocampal VEGF, and BDNF mRNA expression." (PMID 35600989, 2022).
cognitive decline (continued). "In addition, neuromuscular mechanisms, namely, the increased expression of neurotrophic factors (i.e., BDNF), the increase in serotonin and norepinephrine, the regulation of the HPA axis activity, and decreased systemic inflammatory signaling, may be associated with cognitive decline and QoL." (PMID 36556101, 2022). "Considering the conflicting effect of proBDNF/p75NTR and BDNF/TrkB signaling, the imbalance of two signaling cascades may contribute to age-related cognitive decline." (PMID 35887075, 2022). "Consistent with our in vivo data, the oral administration of Noopept has been shown to significantly increase the level of cleaved, mature forms of BDNF and NGF in the brain of wild-type rats, which have been used in aged humans to reduce age-related cognitive decline." (PMID 36614135, 2022). "Astragalus injection treatment could reduce neuroinflammation, reverse BBB dysfunction, prevent neurodegeneration, and upregulate BDNF-CREB pathway during LPS-induced sepsis, ultimately preventing the development of cognitive decline." (PMID 35587259, 2022). "Previous studies have detected cumulative effects of APOE ε4 carriage and BDNF Val66Met carriage on cognitive decline; however, our study was not sufficiently powered to examine the APOE*BDNF interaction." (PMID 33522961, 2021). "Moreover, exogenous FGF1 treatment can reverse diabetes‐induced suppression of brain‐derived neurotrophic factor (BDNF) level and elevated neuronal apoptosis, then ameliorate cognitive decline." (PMID 33788387, 2021). "Other factors by which physical exercise can interfere beneficially for cognition include the release of growth factors such as BDNF, Insulin-like growth factor 1 (IGF-I), and vascular endothelial growth factor (VEGF), possibly providing reserve against later cognitive decline and dementia." (PMID 33584215, 2020). "The third set includes blood neurotrophic biomarkers (e.g., brain-derived neurotrophic factor [BDNF], insulin-like growth factor 1 [IGF-1], and short-chain acylcarnitines [SCACs]) that are found to promote neurogenesis and protect against cognitive decline and incident AD." (PMID 31907024, 2020). "Although cognitive decline is observed after coronary angiography, we did not observe a significant change in serum BDNF levels in the present study." (PMID 30424498, 2018). "The reasons underlying this discrepancy, however, are not yet clear, and further studies on the role of BDNF in hemodialysis-related cognitive decline are required." (PMID 30115946, 2018). "Additionally, intranasal administration BDNF in the APP/PS1 Tg mice decreased the Aβ deposition and reduced the cognitive decline of the mice." (PMID 28377712, 2017). "Given its crucial role in neuronal survival, the lack of BDNF support will exacerbate the cognitive decline observed in AD." (PMID 28134845, 2017). "In animals, decreased BDNF serum levels result in a LTP and memory deficit, thus increasing BDNF availability in the brain may be a viable strategy to counteract cognitive decline with aging." (PMID 26464952, 2015). "Notably, XSB treatment significantly increased BDNF levels and enhanced synaptic density in the hippocampal CA1 region, suggesting that XSB may mitigate synaptic dysfunction and cognitive decline in AD by restoring synaptic integrity and neurotrophic support." (PMID 40689211, 2025). "Moreover, BDNF did not have an effect on cognitive decline, so BDNF was not a mediator of the vitamin D effect on cognitive decline." (PMID 36629701, 2023). "Anatomical and histological observation also found that the up-regulation of proBDNF/mBDNF ratio induced synaptic plasticity impairment, and cognitive decline in depressive episodes and aged, indicating BDNF has bidirectional effects on neuronal function depending on the cleavage of proBDNF." (PMID 36438556, 2022).
cognitive decline (continued). "Additionally, continuous repeated treatment using Astragalus injection could reverse BBB dysfunction, prevent neurodegeneration, and upregulate the BDNF–CREB pathway during LPS-induced sepsis, ultimately preventing the development of cognitive decline." (PMID 35587259, 2022). "In the present study, which included a much bigger sample, but a different scale measuring cognition (i.e., PANSS cognition subscale), the general linear model revealed that BDNF rs6265 did not significantly predict cognitive decline measured with the PANSS cognition scores." (PMID 33926045, 2021). "Therefore, more ZPR1 could mean more BDNF by increasing PPAR-γ transcription, possibly preventing cognitive decline." (PMID 34746842, 2021). "Moreover, individuals in advanced stages of cognitive decline present less or no responsiveness to exercise regulation of BDNF specifically in competences of the executive domains." (PMID 28469588, 2017). "Moreover, the improvement in SCO-induced cognitive decline following acupuncture stimulation at GV20 could also be due to the alleviation of cholinergic neurochemical abnormalities and activation of BDNF and CREB expression." (PMID 25231482, 2014). "The trend toward a cross-sectional association and the lack of longitudinal association, combined with previous published work, may suggest that changes in BDNF occur contemporaneously with cognitive decline, as opposed to preceding decline." (PMID 24670553, 2014). "This could be because the AD group has less variance on these measures, or perhaps because BDNF primarily influences aging-related cognitive decline, as seen in the AD group, but not dramatic disease-related decline as seen in the AD group." (PMID 24086677, 2013). "Moreover, NT-3 and BDNF may compensate for cognitive decline in the early stages of AUD but not in later phases." (PMID 38928583, 2024). "Consequently, learning and memory improvement was evident, suggesting long-term application of ginsenoside Rg1 may postpone cognitive decline via increasing Aβ generation, PKA/CREB activity, as well as brain derived neurotrophic factor (BDNF) content in the brain." (PMID 29344412, 2017). "An anticipated limitation of strategies aimed to enhance endogenous BDNF expression might derive from recent discoveries showing that aging triggers a repressive chromatin state in mice hippocampus at Bdnf promoters, which do not respond to synaptic activity and may contribute to cognitive decline." (PMID 28134845, 2017). "A negative correlation between plasma BDNF concentrations and psychometric test scores (MMSE and CDT) was detected when the relationship between plasma BDNF concentrations and cognitive decline was examined in all subjects (i.e., a combined group with AD and MCI)." (PMID 36979505, 2023).
Parkinson disease (375 papers, 2008 to 2026). A progressive degenerative disorder of the central nervous system characterized by loss of dopamine producing neurons in the substantia nigra and the presence of Lewy bodies in the substantia nigra and locus coeruleus. "For this, 18-month-old mice were used to quantify Syn, BDNF, nNOS, and β-actin as biomarkers of synaptic plasticity, and α-synuclein as a marker of protein aggregates associated with Parkinson’s disease." (PMID 41460391, 2025). "Neuroinflammation and proinflammatory cytokines and signaling downregulate BDNF, implicated in Alzheimer's, Parkinson's, Huntington disease, and MS." (PMID 39935210, 2025). "The synergistic strategy combining stem cell transplantation with endogenous BDNF production addresses both loss of dopaminergic neurons and neurotrophic deficits in Parkinson’s disease." (PMID 41199384, 2025). "Combining stem cell therapy with BDNF provides a potential integrated strategy to address both symptomatic relief and underlying disease mechanisms in Parkinson’s disease." (PMID 41199384, 2025). "Lower BDNF levels have been associated with neurodegenerative conditions, including Alzheimer’s and Parkinson’s diseases, leading to declines in memory and cognitive function." (PMID 39935805, 2024). "The rs6265 single nucleotide polymorphism (SNP) in the gene for brain-derived neurotrophic factor is a common variant that alters therapeutic outcomes for individuals with Parkinson's disease (PD)." (PMID 38746088, 2024). "Previous research has shown that a decrease in overall BDNF levels has been associated with neurodegenerative disorders such as Alzheimer's and Parkinson's disease." (PMID 37822710, 2023). "BDNF has been linked to the pathology of the most common neurodegenerative disorders, such as Alzheimer’s and Parkinson’s disease." (PMID 35625880, 2022). "Decreased BDNF levels are associated with Parkinson’s (PD) and Alzheimer’s (AD) diseases and have also been detected in the serum, aqueous humor, and lacrimal fluid of patients with diabetic retinopathy, AMD, and glaucoma." (PMID 36361771, 2022). "Many of these target genes are implicated in brain-derived neurotrophic factor (BDNF) signaling, whose activity is tightly linked to neurodegenerative syndromes such as Huntington’s, Alzheimer’s and Parkinson’s diseases." (PMID 33363142, 2020). "It has been observed that in patients with Parkinson's disease, the expression of BDNF mRNA decreases, which makes BDNF a candidate gene for susceptibility to this disease." (PMID 33269104, 2020). "An association between Parkinson's disease and the rs6265 polymorphism of BDNF has already been suggested." (PMID 33269104, 2020). "In humans, BDNF mutations contribute to neurodegenerative disorders such as Alzheimer’s, Huntington’s, and Parkinson diseases." (PMID 32430868, 2020). "We have also discussed the effects of current therapies on BDNF/TrkB signaling in Parkinson’s disease patients and the mechanisms underlying the mutation-mediated acquisition of resistance to therapies for Parkinson’s disease." (PMID 31963575, 2020). "While other studies have investigated BDNF haplotypes including rs2049045 and the relation with risk of Parkinson disease." (PMID 33269104, 2020). "Disruption of BDNF and its downstream signaling pathways have been observed in many neurodegenerative diseases such as Alzheimer’s, Parkinson’s and Huntington’s diseases, underlining the importance of BDNF." (PMID 26518675, 2016). "Accordingly, inhibiting BDNF expression by antisense oligonucleotide infusion causes loss of nigral DA neurons and mimics parkinsonism in adult rats." (PMID 26198255, 2015). "Altered BDNF signaling has been implicated in several neurodegenerative diseases, including Huntington's, Alzheimer's and Parkinson's diseases and relevant therapeutic strategies for these disorders are aimed at increasing BDNF levels in the brain." (PMID 21912641, 2011).
Parkinson disease (continued). "Accordingly, altered activities of BDNF and other neurotrophins have been implicated in several neurodegenerative diseases, including Huntington's, Alzheimer's and Parkinson's diseases." (PMID 21912641, 2011). "Such a therapeutic approach would be applicable to several neurodegenerative diseases, including Huntington's, Alzheimer's and Parkinson's diseases, in which decreased BDNF signaling has been implicated." (PMID 21912641, 2011). "In a medical context, decreases in relative levels of BDNF are a marker of neurological dysfunction and neuronal loss and are associated with neurodegenerative diseases, including Alzheimer’s, Huntington’s, and Parkinson’s disease." (PMID 40073124, 2025). "The neuroprotective effects of PF against Parkinson’s disease could be associated with the modulation of the brain-derived neurotrophic factor (BDNF) and the activation of the downstream AKT/PI3K signaling pathway." (PMID 40650274, 2025). "Similarly, in Parkinson's disease, characterized by the progressive loss of dopaminergic neurons, BDNF has emerged as a promising factor for enhancing neuronal survival and function." (PMID 39568824, 2024). "Moreover, SITG also enhanced memory performance in rats with Parkinson’s disease (PD) by increasing levels of BDNF, which helps to protect against neuronal loss and the deterioration of dendritic spines." (PMID 39766390, 2024). "Interestingly, a higher frequency of familial Parkinson's disease has been associated with BDNF polymorphism." (PMID 39712854, 2024). "Additionally, literature revealed that AECs increased the lifespan of dopamine (DA) neurons by generating biologically active neurotrophins, including BDNF and neurotrophin-3 (NT-3), preventing DA neurons loss in rats with Parkinson's disease." (PMID 37711653, 2023). "Consequently, BDNF deficiency has been associated with some neurological disorders such as Alzheimer’s, Parkinson’s or Huntington’s diseases." (PMID 36827132, 2023). "BDNF might also be associated with IBD comorbidities: a recent meta-analysis demonstrated that patients with IBD have an increased risk of developing Parkinson’s disease, in which BDNF plays an important role and is extensively studied." (PMID 36294343, 2022). "One recent study has linked the BDNF genotype and response to long-term pharmacological therapy in Parkinson’s disease patients, suggesting a role of BDNF in prediction and counseling in the treatment of Parkinson’s disease." (PMID 35625880, 2022). "In addition, they found that BDNF levels were associated with disease duration, Unified Parkinson's Disease Rating Scale score, H-Y staging and treatment with L-DOPA." (PMID 34381349, 2021). "In addition, circMap1a also interacts with the mRNAs of Myo6, which is required for BDNF-mediated neurotransmission and Park7, associated to Parkinson’s Disease and encoding a DJ-1 protein protecting brain cells from oxidative stress." (PMID 32849796, 2020). "Moreover, RBFOX1 dysregulation has been associated with intellectual disability, autism, epilepsy and Parkinson disease, pathologies that have been associated with alterations in BDNF signaling as well." (PMID 31429825, 2019). "Indeed, polymorphisms in the Bdnf gene have been linked to increased risk of LID in Parkinson’s disease patients, and striatal overexpression of BDNF increases susceptibility to LID in hemiparkinsonian rodents." (PMID 30497382, 2018). "Overall, these results suggest that n- 3 PUFA modulation of BDNF expression may form part of the mechanism underlying n-3 PUFA-mediated neuroprotection in an animal model of parkinsonism." (PMID 30233293, 2018). "BDNF is also strongly implicated in the pathogenesis of dementia, AD, and Parkinson's disease." (PMID 30008787, 2018). "The reduction of BDNF expression in Parkinson’s disease substantia nigra (SN) might contribute to the death of dopaminergic neurons because inhibiting BDNF expression in the SN causes parkinsonism in the rat." (PMID 26198255, 2015).